AMPH (amphiphysin)
Diseases named in the same sentence as AMPH in open-access papers (continued):
Sharing a sentence is not in itself a finding about the gene and the disease.
paraneoplastic neurological syndromes (6 papers, 2008 to 2024). "One of them reported five cases of anti-amphiphysin associated paraneoplastic neurological syndromes." (PMID 28468645, 2017). "Paraneoplastic neurological syndromes (PNS) are remote effects of cancer and often are associated with high concentrations of so-called well-characterized onconeural antibodies (anti-Hu, Yo, Ri, CV2/CRMP5, Ma1, Ma2, and amphiphysin) that help to establish the diagnosis." (PMID 28068933, 2017). "Other autoimmune encephalitis (AE)-related antibodies against GFAP and paraneoplastic neurological syndrome (PNS)-related antibodies, including anti-Hu, anti-Ri, anti-Yo, anti-Ma2, anti-CV2, and anti-amphiphysin, were absent from the CSF and serum, respectively." (PMID 39267735, 2024).
autoimmune encephalitis (5 papers, 2020 to 2023). Inflammation of the brain secondary to an immune response triggered by the body itself. "An analysis of the clinical features of autoimmune encephalitis accompanied by anti-amphiphysin antibodies." (PMID 37090693, 2023). "Autoimmune encephalitis with anti-amphiphysin antibodies has a variety of clinical manifestations." (PMID 37090693, 2023). "In addition to these, serum autoimmune encephalitis (NMDA, CASPR-2, LGI-1, GABA-B, AMPA1, AMPA2), paraneoplastic (anti-GAD, Ma1/Ma2, CRMP-5, amphiphysin, Yo, PCA2, Hu, Ri) antibody panels and anti- were assessed in 21 and 19 patients respectively and all were negative." (PMID 37152622, 2023).
Alzheimer disease (4 papers, 2016 to 2025). A progressive, neurodegenerative disease characterized by loss of function and death of nerve cells in several areas of the brain leading to loss of cognitive function such as memory and language. "Furthermore, although not included in the present study, we have noticed amphiphysin antibody positivity in some AD (Alzheimer’s disease) and PD (Parkinson’s disease) patients." (PMID 37090693, 2023).
encephalomyelitis (3 papers, 2015 to 2025). Inflammation of the brain and the spinal cord. "Variants of SPS have also been described, including partial forms restricted to the limbs, progressive encephalomyelitis with rigidity and myoclonus, and paraneoplastic forms, which are often associated with amphiphysin or glycine receptor antibodies." (PMID 41393707, 2025). "Anti-amphiphysin antibodies have been identified in a few patients with PNS and SCLC, whose manifestations included encephalomyelitis/sensory neuropathy, cerebellar degeneration and opsoclonus." (PMID 25574194, 2015).
Encephalopathy (3 papers, 2015 to 2025). Encephalopathy is a term that means brain disease, damage, or malfunction. "Autoantibodies targeting amphiphysin are associated with several neurological disorders, including sensory neuronopathy and encephalopathy." (PMID 26441823, 2015). "Therefore, we diagnosed the patient with encephalopathy related to anti-AMPH antibodies." (PMID 37416304, 2023). "Based on her symptoms, which did not contradict encephalopathy, and the possible detection of anti-AMPH antibodies, we suspected that she had anti-AMPH syndrome." (PMID 37416304, 2023).
non-small cell lung carcinoma (3 papers, 2016 to 2022). A group of at least three distinct histological types of lung cancer, including non-small cell squamous cell carcinoma, adenocarcinoma, and large cell carcinoma. "The relationship between miR-425 and AMPH has been reported that miR-425 regulates cell proliferation, migration, and apoptosis by targeting AMPH in non-small-cell lung cancer." (PMID 33274225, 2020).
epilepsy (2 papers, 2013 to 2023). A brain disorder characterized by episodes of abnormally increased neuronal discharge resulting in transient episodes of sensory or motor neurological dysfunction, or psychic dysfunction. "AMPH1 codes for amphiphysin I, which is an important regulator of synaptic vesicle endocytosis when massive amounts of Ca2+ flow into presynaptic terminals, a phenomenon observed in epilepsy." (PMID 24278214, 2013).
Lambert-Eaton myasthenic syndrome (2 papers, 2013 to 2025). Lambert-Eaton myasthenic syndrome (LEMS) is an autoimmune, presynaptic disorder of neuromuscular transmission characterized by fluctuating muscle weakness and autonomic dysfunction frequently associated with small-cell lung cancer (SCLC). "Additionally, Anti-Yo, Anti-Ma, and Anti-amphiphysin antibodies also presented with paraneoplastic visual impairment syndrome, subacute sensory neuronopathy, acute sensory-motor neuropathy, and Lambert-Eaton myasthenic syndrome, reflecting a diverse range of clinical manifestations." (PMID 41488641, 2025).
Opsoclonus (2 papers, 2015 to 2024). "The humoral immunopathogenesis in paraneoplastic opsoclonus has been elucidated by the detection of a multitude of antineuronal antibodies: Ri, YO, Hu, Ma1, Ma2, amphiphysin, CV2, Zic2, and neurofilaments." (PMID 38883074, 2024).
Pruritus (2 papers, 2023). Pruritus is an itch or a sensation that makes a person want to scratch. "We thus describe a case of anti-amphiphysin antibody-positive SPS, which initially manifested with generalized pruritus." (PMID 36968894, 2023).
tauopathy (2 papers, 2014 to 2021). Neurodegenerative disorders involving deposition of abnormal tau protein isoforms (tau proteins) in neurons and glial cells in the brain. "Recently, we showed that Amphiphysin-1 (AMPH1) protein's abundance is reduced in the central nervous system (CNS) of the tauopathy mouse model JNPL3 and AD brains." (PMID 24454278, 2014). "Previously, we reported that the abundance of the synaptic protein Amphiphysin-1 (AMPH1) is reduced in the central nervous system (CNS) of the JNPL3 tauopathy mouse model and AD brains." (PMID 24454278, 2014). "However, decreasing levels of AMPH have been identified in a tauopathy mouse model, possibly reflecting mechanisms relevant to AD." (PMID 33653397, 2021).
autonomic neuropathy (1 paper, 2024). An inherited or acquired peripheral neuropathy affecting the autonomic nervous system. "Therefore, this is a valuable case with anti-amphiphysin antibodies, presenting multiple neurological symptoms, including bulbar palsy, cerebellar ataxia, autonomic neuropathy, and peripheral neuropathy." (PMID 39184604, 2024).
blepharospasms (1 paper, 2024). "An adult female presented with a sudden onset of chest pain, unilateral extremity weakness, blepharospasms, and muscle spasms, with positive voltage-gated potassium channel (VGKC) antibody and positive neuronal antibody (amphiphysin) in serum." (PMID 39376863, 2024).
cerebellar ataxia (1 paper, 2024). A neurological syndrome characterized by clumsy and uncoordinated movement of the limbs, trunk, and cranial muscles. "A case of a 74-year-old man with anti-amphiphysin antibody and multiple symptoms, including bulbar palsy along with cerebellar ataxia, who responded to treatment with intravenous cyclophosphamide is reported." (PMID 39184604, 2024).
cyst (1 paper, 2023). A sac-like closed membranous structure that may be empty or contain fluid or amorphous material. "Expression of Amphiphysin (Amph) supported the conclusion that the bifurcation in the cyst cell lineage after cluster 58 represents cyst cells associated with spermatocytes." (PMID 36795469, 2023).
demyelination (1 paper, 2025). "Paraneoplastic syndromes such as those associated with anti-Hu, anti-Yo, anti-Ma2, anti-Ri, anti-CV2, or anti-amphiphysin antibodies can cause multifocal neurological deficits and MRI findings that resemble demyelination or infarction." (PMID 41426809, 2025).
epileptic syndromes (1 paper, 2022). "The most frequent clinical syndromes were AE, including limbic and basal ganglia encephalitis (57/94, 61%; GABAAR, D2R, GABABR, AMPAR, amphiphysin, and mGluR5), and isolated epileptic syndromes (15/94, 16%; GlyR, GABAAR)." (PMID 35515348, 2022).
Hyponatremia (1 paper, 2025). An abnormally decreased sodium concentration in the blood. "Despite the phenotypic resemblance to SPS, the movement disorders secondary to hypoadrenalism displayed a distinctive triad: ACTH and/or cortisol deficiency (or related hyponatremia), negative anti-GAD (or anti-amphiphysin) antibodies, and limited response to benzodiazepine." (PMID 41141341, 2025).
invasive ductal carcinoma of the breast (1 paper, 2021). "Case Description: We present a case of anti-amphiphysin antibody (Ab)-associated paraneoplastic SLS, in an 83-year-old woman with invasive ductal carcinoma of the breast." (PMID 34777203, 2021).
keloid (1 paper, 2026). An irregularly shaped, elevated mark on the skin caused by deposits of excessive amounts of collagen during wound healing. "AMPH and TNFRSF9 are promising diagnostic biomarkers for keloid, while quercetin from Aloe vera targets HAS2 and IL6, offering therapeutic potential." (PMID 41544047, 2026). "Through machine learning-based feature selection, two feature genes—AMPH (Amphiphysin) and TNFRSF9 (Tumor Necrosis Factor Receptor Superfamily Member 9)—were identified as potential keloid biomarkers." (PMID 41544047, 2026). "Future studies should prioritize experimental validation of AMPH/TNFRSF9 in larger cohorts, functional characterization of IL6/HAS2 in keloid models and development of quercetin topical formulations to address the clinical need for safe and effective anti-keloid treatment." (PMID 41544047, 2026). "While both genes showed elevated expression in keloids (log2FC > 1), only TNFRSF9 reached statistical significance (p = 0.0091 vs p = 0.1 for AMPH) in the testing cohort GSE44270 (n = 12; 9 keloid and 3 normal)." (PMID 41544047, 2026).
large-cell neuroendocrine carcinoma of (1 paper, 2023). "This is the first known report in the literature that a case with both positive anti-PCA1 (Yo) and anti-amphiphysin antibodies together and underlying small-cell and large-cell neuroendocrine carcinomas." (PMID 37456392, 2023). "Following the high-dose methylprednisolone therapy, anti-PCA1 (Yo) and anti-amphiphysin antibodies were positive and the tissue pathology report confirmed combined small-cell carcinoma and large-cell neuroendocrine carcinoma of the lung." (PMID 37456392, 2023).
lung adenocarcinoma (1 paper, 2019). A carcinoma that arises from the lung and is characterized by the presence of malignant glandular epithelial cells. "Four GAD-positive patients, without amphiphysin antibodies, developed cancer (breast, prostate, skin, lung adenocarcinoma) several years after onset of SPS but all survived cancer treatment." (PMID 30606131, 2019).
Morvan syndrome (1 paper, 2024). Morvan syndrome is a rare, life-threatening, acquired neurologic disease characterized by neuromyotonia, dysautonomia and encephalopathy with severe insomnia. "This atypical presentation of Morvan syndrome in a female identifies a novel association of amphiphysin positivity in this rare disease." (PMID 39376863, 2024).
myasthenia gravis (1 paper, 2024). Myasthenia gravis (MG) is a rare, clinically heterogeneous, autoimmune disorder of the neuromuscular junction characterized by fatigable weakness of voluntary muscles. "Some forms of SPS may be linked with other immune processes (e.g., myasthenia gravis or progressive encephalomyelitis with rigidity and myoclonus) or represent a paraneoplastic process, such as in the context of positive anti-amphiphysin antibodies." (PMID 39097681, 2024).
Myokymia (1 paper, 2025). Myokymia consists of involuntary, fine, continuous, undulating contractions that spread across the affected striated muscle. "A potential confounding factor is the presence of low-level amphiphysin antibodies initially detected, but literature searches show no reports linking amphiphysin with symptoms such as myokymia or facial spasms." (PMID 41020014, 2025).
schizophrenia (1 paper, 2019). A major psychotic disorder characterized by abnormalities in the perception or expression of reality. "Therefore, the hypersensitivity to AMPH in our female tgDISC1 × JIA animals could be caused by a synergistic action of tgDISC1 and JIA on dopaminergic tone as suggested by the two-hit hypothesis of schizophrenia." (PMID 31057438, 2019).
Sepsis (1 paper, 2021). Sepsis is defined as life-threatening organ dysfunction caused by a dysregulated host response to infection. "Through searching the sepsis-related publication of the key genes, CCR7, CXCR3, FYN, CEACAM1, CD81, AMPH, HLA-DMA, and G protein-coupled receptors (GPR18) were considered to be key genes." (PMID 34484417, 2021).
Stroke (1 paper, 2014). Sudden impairment of blood flow to a part of the brain due to occlusion or rupture of an artery to the brain. "In fact, two-way analysis of variance indicated that only AMPH+REHAB animals recovered to levels of performance that were similar to pre-stroke values." (PMID 25229819, 2014).
tuberculous meningitis (1 paper, 2012). "We validated amphiphysin, neurofascin and ferritin light chain using immunohistochemistry which confirmed their differential expression in tuberculous meningitis." (PMID 23198679, 2012).
virus infection (1 paper, 2016). "On the other hand, the Cterminus contains Src-homology 3 (SH3) binding motifs for the localization of cellular amphiphysins Amph1 and BIN1/Amph2 following virus infection which promote Alphavirus genome replication." (PMID 27812412, 2016).
tumor (14 papers, 2017 to 2025). "After immunotherapy and tumor resection, the patient's serum was analyzed using immunoprecipitation, which showed a decrease in the level of anti-AMPH antibodies." (PMID 37416304, 2023). "Histopathology revealed amphiphysin protein expression and accompanying immune cell infiltration within the tumor tissue, suggesting a possible paraneoplastic origin of amphiphysin-associated PNSs in this case." (PMID 36685551, 2022). "In this case, immunohistochemical amphiphysin-Abs positivity was shown in appendiceal tumor tissue, confirming that the syndrome was triggered by the tumor." (PMID 36685551, 2022). "Here, we first report a patient with aGCC who developed LE related to amphiphysin-Abs after tumor removal." (PMID 36685551, 2022). "The presence of a tumor in her body has been the focus of our attention since the antibody amphiphysin in serum was positive." (PMID 33835270, 2021). "Amphiphysin is an intraneuronal protein that is targeted in 5-10% of PNS cases, and the presence of anti-amphiphysin antibodies has been listed as a significant risk factor for tumor occurrence (>80%)." (PMID 37090693, 2023). "We observed a strong reduction of AMPH staining in xenografic tumor tissue bearing MKN1 KO cells." (PMID 35778385, 2022). "Blood examination showed tumor marker elevation and the presence of anti-amphiphysin antibodies." (PMID 35899265, 2022). "Both serum and CSF antineuronal antibodies (Hu, Yo, Ri, CV2, amphiphysin, Ma2/Ta) were negative, as were tumor markers." (PMID 41246321, 2025).
cancer (12 papers, 2012 to 2026). A tumor composed of atypical neoplastic, often pleomorphic cells that invade other tissues. "Paraneoplastic SPS, often linked with anti-amphiphysin antibodies, typically occurs in cancer patients and can present various symptoms." (PMID 39193054, 2024). "Anti-amphiphysin antibody is a high-risk antibody for cancer." (PMID 39184604, 2024). "Cancer is detected in about 80% of patients with anti-amphiphysin antibodies, most commonly lung cancer (70%, mainly small cell lung cancer) and breast cancer (25%)." (PMID 39184604, 2024). "GAD65 was the most common autoantigen in patients with cancer and SPSSDs, followed by amphiphysin and GlyR." (PMID 37859648, 2023). "If the patient had a nonclassical syndrome, then a well-characterized onconeuronal antibody, such as anti-Hu, Yo, CV2, Ri, MA2, or amphiphysin, with the diagnosis of cancer within five years of development of neurological symptoms was also sufficient for diagnosis." (PMID 35602787, 2022). "Inspired by previous reports suggesting a paraneoplastic etiology in rare cases of cancer-associated NMOSD, this is the first study systematically investigating the seroprevalence of onconeural antibodies (anti-Hu, Yo, Ri, CV2/CRMP5, Ma1, Ma2, Zic4, SOX1, Tr, and amphiphysin) in NMOSD patients." (PMID 28068933, 2017). "Regarding treatment of stiffness in the anti-amphiphysin group, nine patients were reported to have a good response to high dose benzodiazepine (>50 mg/day); four patients were steroid responsive; and three patients had a dramatic improvement after cancer excision/chemotherapy." (PMID 27800287, 2015). "However, when limited to cases of non-stiff anti-amphiphysin syndrome, cancer is detected in only 35% of cases." (PMID 39184604, 2024).
infection (3 papers, 2011 to 2025). The state of being infected such as from the introduction of a foreign agent such as serum, vaccine, antigenic substance or organism. "However, the survival rate of animals infected with P. aeruginosa was not evidently impacted by the absence of AMPH-1, suggesting that the decrease in infection response caused by RAB-10 deficiency is not due to impaired recycling transport." (PMID 39087719, 2025). "However, recruitment of amphiphysin to RCs was also seen upon infection with viruses encoding nsP3s that lacked the SH3 binding site and failed to physically interact with amphiphysin-1 or -2 in our co-precipitation assays." (PMID 22114558, 2011).
neuromuscular disease (1 paper, 2012). "This review discusses the pathophysiology of the related neuromuscular diseases on the basis of animal models developed for proteins of the myotubularin, amphiphysin, and dynamin families." (PMID 22496665, 2012).
AMPH also shares sentences with these, for which no sentence is quoted: Hodgkins lymphoma (5 papers); Anxiety (3); neurological diseases (3); peripheral neuropathy (3); testicular cancer (3); thymoma (3); autoimmune disease (2); centronuclear myopathy (2); cognitive deficits (2); colon carcinoma (2); depression (2); neuroblastoma (2); ovarian carcinoma (2); Sensory neuropathy (2); Achalasia (1); acute disseminated encephalomyelitis (1); angiosarcoma (1); autoimmune neuropathy (1); autonomic dysfunction (1); Brain atrophy (1); cauda equina syndrome (1); cerebellar degeneration (1); Chorea (1); cryptococcosis (1); dysautonomia (1); early infantile epileptic encephalopathy (1); fungal infections (1); Gait ataxia (1); gastric adenocarcinoma (1); gastric cancer (1).
A further 30 diseases each share a sentence with AMPH in 1 paper.